CRP (C-reactive protein)
Diseases named in the same sentence as CRP in open-access papers (continued):
Sharing a sentence is not in itself a finding about the gene and the disease.
atherosclerosis (continued). "However, atherosclerosis patients had a significantly higher level of the C-reactive protein (CRP) than the control group (p < 0.001)." (PMID 32336973, 2020). "Peripheral eosinophilia may be an indicator for kidney damage and the severity of this marker may predict future irreversible interstitial damage, similar to the utility of CRP as a good clinical marker for inflammation and atherosclerosis." (PMID 31931743, 2020). "Thus, mutant CRP conferred protection against atherosclerosis, providing a proof of concept that a local inflammation-induced structural change in wild-type CRP is a prerequisite for CRP to control the development of atherosclerosis." (PMID 32849641, 2020). "CRP is a general biomarker of inflammation, however slightly elevated CRP levels in blood can be an indicator of atherosclerosis, and have been shown to be a predictor for heart attacks, stroke, and sudden cardiac death for patients with and without a history of CVD36–39." (PMID 32411827, 2020). "The CRP as an active mediator of atherosclerosis could promote arterial endothelial activation and macrophage recruitment." (PMID 32358950, 2020). "It has been shown that CRP can activate complement and is associated with impaired systemic endothelial vascular reactivity in patients with CAV as well as in patients with native atherosclerosis." (PMID 33014277, 2020). "However, the evidence showing benefits of CPAP usage on inflammatory markers like hs CRP and IL 6 (which serve as a connection between inflammation and atherosclerosis) is inconclusive." (PMID 32821638, 2020). "The aim of this study was to test the hypothesis that C-reactive protein (CRP) protects against the development of atherosclerosis and that a conformational alteration of wild-type CRP is necessary for CRP to do so." (PMID 32849641, 2020). "In a study of 67 hypertensive and 30 healthy subjects, Mutluay and colleagues found hyperuricemia is an independent predictor for early atherosclerosis in hypertensive subjects, and inflammation play an important role during the process of atherosclerosis, in which hs-CRP is an important marker." (PMID 32968406, 2020). "There is an ongoing debate on whether hs-CRP is an indicator of inflammation or whether it contributes to the development of atherosclerosis." (PMID 33094574, 2020). "Indeed, there is growing evidence that proinflammatory cytokines, such as IL-1, IL-6, TNF-α and CRP, contribute to atherosclerosis and adverse cardiovascular outcomes and predict mortality in ESRD patients." (PMID 32770957, 2020). "In addition, CRP participates in the pathogenesis of atherosclerosis through multiple ways such as induction of vascular endothelial dysfunction and promoting adhesion of monocyte/macrophage to the vascular endothelium, inter alia." (PMID 32831861, 2020). "Thus, CRP has an active role in the pro-inflammatory response to cerebrovascular disease including ischemia and atherosclerosis, diseases that negatively impact white matter integrity and underlying white matter microstructure." (PMID 33192454, 2020). "The elevated CRP, in part, reflects the burden of atherosclerosis, but it may also reflect other factors, as it remained an independent risk factor for ischemic stroke." (PMID 30987675, 2019). "In a multivariate analysis, the prognostic value was independent of the other inflammatory biomarkers (IL-6, CRP) and classical risk factors of atherosclerosis." (PMID 31687090, 2019). "Leibovitch and colleagues discussed vascular insufficiency which may have a role in the development of NTG along with high levels of CRP seen in atherosclerosis." (PMID 31788489, 2019). "The high levelsof CRP and hypoalbuminemia present in our patients may thus reflect the presence ofmalnutrition-inflammation-atherosclerosis (MIA syndrome), as they were patients withcalcification that progressed significantly within a short period of time." (PMID 31419271, 2019).
atherosclerosis (continued). "A logistic regression model was built in 697 participants to evaluate the possible predictive role of selected variables (age, male gender, HBP, T2D, ACPA, mean values of CRP during the follow-up, remission) on the likelihood of having subclinical atherosclerosis, after 36 months." (PMID 31481105, 2019). "On the one hand, classic atherosclerosis may thus be in part the result of “low-grade inflammation,” marked by mildly elevated CRP levels." (PMID 31672136, 2019). "Since CRP has been found to localize with LDL and macrophages in atherosclerotic lesions in both humans and experimental animals, CRP has been implicated in modulating the pathogenesis of atherosclerosis." (PMID 31379851, 2019). "Moreover, the Monitoring Trends and Determinants in Cardiovascular Disease study compared suPAR with CRP and showed that suPAR is more related to endothelial dysfunction and atherosclerosis than CRP." (PMID 30820636, 2019). "In addition, atomic bomb survivors exposed to high doses are more prone to the development of atherosclerosis and demonstrated signs of general inflammation, with increased levels of IL-6 and C-reactive protein (CRP)." (PMID 30377700, 2019). "These pro-inflammation proteins include IL-1β, IL-6, tumor necrosis factor α (TNFα), interferon γ (IFNγ), complement proteins, C-reactive protein (CRP), etc., which are implicated in the pathogenesis and progression of atherosclerosis and intravascular thrombosis." (PMID 31068769, 2019). "Interleukin- (IL-) 6, one of the most potent drivers of CRP production, is released from activated leukocytes in response to infection or trauma and from vascular smooth muscle cells in response to atherosclerosis, but CRP is also released by both skeletal muscle and adipose tissue." (PMID 31827693, 2019). "The plasma biomarkers Lp-PLA2 activity and mass, and CRP were markers of PAD risk, implying that they might be useful biomarkers for subclinical atherosclerosis and atherosclerotic disease." (PMID 30948779, 2019). "Specifically, IL-6 is a cytokine derived from T lymphocytes, macrophages and adipocytes, and acts via its membrane-bound or soluble receptor, stimulating C-reactive protein, fibrinogen hepatic synthesis, and joint inflammation and accelerating atherosclerosis processes." (PMID 30223482, 2018). "C-reactive protein is elevated in cardiovascular disorders and is a mediator of atherosclerosis." (PMID 29706967, 2018). "Serum level of CRP is a determinant of atherosclerosis severity." (PMID 30524759, 2018). "However it has also been reported that CRP is a valuable predictor of cardiovascular risk in CKD and it also plays a role in atherosclerosis." (PMID 29902980, 2018). "Monomeric CRP has been involved in ischemic heart disease, therefore pCRP dissociation to mCRP modulates inflammation in both acute (cardiac ischemia/reperfusion) and chronic (atherosclerosis) inflammatory processes." (PMID 29552019, 2018). "Given that atherosclerosis is an inflammatory disease, a lower Gensini score and lower CRP levels in the low RDW quartile may indicate a lower inflammatory activity in patients in this group." (PMID 29548288, 2018). "C-reactive protein (CRP) is probably a mediator of atherosclerosis and may increase the vulnerability of an atherosclerotic plaque to rupture." (PMID 30524653, 2018). "Clinical trials involving canakinumab, a monoclonal antibody against IL-1β, has shown a significant reduction of major cardiovascular incidents in patients with atherosclerosis, by reducing the total levels of plasma IL-6 and CRP compared to those given a placebo." (PMID 30333009, 2018). "Atherosclerosis has seen intense research activity targeting reductions in C-reactive protein (CRP) as a result of retrospective analysis of primary prevention trials with statins which found that the benefits of statins were not solely due to their reduction of low-density lipoprotein (LDL)." (PMID 30453474, 2018).
atherosclerosis (continued). "Indeed, therapies associated with a reduction in systemic CRP levels are successfully used in other chronic inflammatory diseases such as atherosclerosis, where CRP is an important player." (PMID 29725335, 2018). "Integrative interpretation of a subset of measures, e.g., cIMT, CRP, and sICAM-1, and calculation of the ApoB100/ApoA1 ratio might help in the early estimation of premature atherosclerosis in psoriatic patients." (PMID 29535705, 2018). "Interestingly, it has been suggested that CRP modulates the process of atherosclerosis by inducing endothelial dysfunction and uncoupling endothelial nitric oxide synthase (eNOS) mRNA expression." (PMID 30524759, 2018). "Furthermore, elevated circulating CRP levels are an independent risk factor for CVD, including myocardial infarction, stroke, and atherosclerosis." (PMID 29752343, 2018). "Still, our results on inflammation and atherosclerosis confirm previous studies where carotid atherosclerosis was independently associated with WBCC but not CRP." (PMID 28376102, 2017). "Therefore, in asymptomatic subjects with NAFLD, especially those with high hs-CRP, prevention of subclinical atherosclerosis through lifestyle modification and further reversal of fatty liver and systemic inflammation is critical." (PMID 28686633, 2017). "Since CRP increases vastly during inflammation, complement may exacerbate this condition through CRP and thus play a role in the pathophysiology of atherosclerosis." (PMID 28900428, 2017). "Chronic status of endotoxemia contributes to chronic inflammation and the development of atherosclerosis, which might be supported by our finding that endotoxin level was positively correlated with CRP." (PMID 28701158, 2017). "On the other hand, the correlations between ADMA and cIMT indicate a role for endogenous NO synthase inhibitors in the development of later stages of atherosclerosis in individuals with high levels of systemic inflammation, which concurs with reports linking elevated CRP with cIMT in RA population." (PMID 28183353, 2017). "In conclusion, this study identifies CRP as a strong C1q recruiter and complement facilitator on CC, which may be highly relevant for the development of atherosclerosis." (PMID 28900428, 2017). "This may explain some of the controversy regarding mononuclear cell signaling by CRP and its role in atherosclerosis." (PMID 27621811, 2016). "Mechanistic studies have demonstrated that CRP and oxLDL may be interacting in concert to promote atherosclerosis." (PMID 26938991, 2016). "Moreover, RGPM suppressed the levels of CRP in plasma and down-regulated blood pressure, compatible with the processes of atherosclerosis." (PMID 26961224, 2016). "However, some experiments also shows that CRP activate the complement system in the atherosclerosis site, by biding to phosphocholine, so inhibiting the lectin complement pathway." (PMID 27846846, 2016). "It is, however, unlikely that monomeric CRP participates in TRALI as monomeric CRP has been linked to different types of disease pathologies like atherosclerosis and myocardial infarction without antibody involvement." (PMID 27793007, 2016). "On the other hand, CRP levels may be a marker for arteriolosclerosis or small-vessel disease, as they are for atherosclerosis." (PMID 27555819, 2016). "We hypothesized that human CRP promotes ADSC-induced angiogenesis in the setting of atherosclerosis." (PMID 27526687, 2016). "Our study revealed a significant association of CRP and SAA levels with approximately all of the studied atherosclerosis-related traits, including glucose metabolism, renal function, levels of various adipokines, and inflammatory markers, as well as adiposity and BP status." (PMID 27313400, 2016). "Our findings will provide new evidence that CRP could promote growth of the vasa vasorum in atherosclerosis." (PMID 27526687, 2016). "Inflammation plays a central role in atherosclerosis, and CRP is a critical factor in inflammation." (PMID 27448600, 2016).
atherosclerosis (continued). "Systemic inflammation as expressed by serum CRP, was similar in our groups of healthy subjects and dyslipidemic patients, pointing to very early modifications occurring in our patients in the “atherosclerosis continuum” from functional disturbances to ouvert diseases." (PMID 26822994, 2016). "We conducted a cross-sectional study of a tertiary care cohort of psoriasis patients using coronary artery calcium (CAC) score and carotid intima-media thickness (CIMT) to detect atherosclerosis, along with high sensitivity C-reactive protein (hsCRP) to measure inflammation." (PMID 27448600, 2016). "Atherosclerosis is essentially an inflammatory disease, with levels of different biomarkers of inflammation such as C-reactive protein (CRP), interleukin-6, and N-terminal pro-hormone B-type natriuretic peptide (NTproBNP) correlating closely with subsequent cardiac events." (PMID 27375684, 2016). "A correlation between CRP and FIMT in NDRA patients corroborated with the findings of previous studies reporting an association between RA activity, inflammatory markers and subclinical atherosclerosis or increased CV morbidity and mortality." (PMID 26648990, 2015). "CRP and atherosclerosis had a link in the beginning as biomarker v/s mediator of atherosclerosis." (PMID 25822970, 2015). "Moreover, an increasing number of data suggest that CRP directly participates in the initiation and progression of atherosclerosis through multiple activities in the inflammatory response." (PMID 26131983, 2015). "As it is possible to assay the CRP levels with a high-sensitivity method, it became possible to precisely determine low CRP levels that indicate mild inflammation, assumed to contribute to atherosclerosis pathogenesis." (PMID 25839035, 2015). "This study brings new insights that oxLDL and CRP may play a direct role in promoting the inflammatory component of atherosclerosis." (PMID 25056585, 2015). "In the placebo group a small increase in both CRP and sP-selectin could be seen, which might reflect an age-related increase in the atherosclerosis process." (PMID 26375288, 2015). "In this study, blood samples from more than 440 elderly community inhabitants in an intervention study using selenium and coenzyme Q10 combined as a dietary supplement were evaluated regarding the biomarkers C-reactive protein, and sP-selectin, which are markers for inflammation and atherosclerosis." (PMID 26375288, 2015). "The included studies used different blood-derived markers of atherosclerosis, such as: high sensitivity CRP (hsCRP), vasogenic endothelial growth factor (VEGF), interleukins (IL) IL-6 and IL-18, osteopontin (OPN), osteoprotegerin (OPG) and tumor necrosis factor-alpha (TNF-α)." (PMID 25984600, 2015). "C-reactive protein plays an important role in the pathogenesis of atherosclerosis." (PMID 26193292, 2015). "The interaction of tissue-bound mCRP with anti-CRP antibodies in vascular tissue has been suggested to promote the production of atherosclerosis and could therefore link elevated anti-CRP serum levels with chronic vascular disease in SLE patients." (PMID 26089599, 2015). "Fibrinogen, PWV and also cIMT values was significantly higher in RA patients compared to controls (p<0.001) as was CRP (p<0.05); moreover, cIMT was on average above 0.9 mm, considered the upper reference limit for preclinical atherosclerosis according to ESH-ESC guidelines." (PMID 26241902, 2015). "High sensitivity C-reactive protein (hs-CRP) is a marker of inflammation that may predict subclinical atherosclerosis." (PMID 25595197, 2015). "CRP can be used to predict cardiovascular events in patients with stable angina pectoris and in apparently healthy people, through revealing local inflammation in atherosclerosis." (PMID 25864817, 2015).
atherosclerosis (continued). "Extreme atherosclerosis in these patients and higher vascular inflammation during the index procedure (mean CRP levels in RC 6 vs. RC 5 vs. RC 4: 12.55 vs. 3.56 vs. 2.46 mg/dL, p = 0.027) might have negatively influenced the DCB outcome in these patients." (PMID 26599128, 2015). "CRP, which is an acute phase reactant produced by the liver, is not only a marker for CVD, but is also associated with the development and progression of atherosclerosis." (PMID 26381729, 2015). "Only cIMT and CRP are accepted surrogate markers of atherosclerosis, and best documented in adults." (PMID 26408307, 2015). "The effects on inflammation/atherosclerosis were evaluated through analyses of CRP and sP-selectin." (PMID 26375288, 2015). "Even in type 1 diabetes patients without chronic complications there is a mild chronic inflammatory state, which can be observed as an elevation of acute phase proteins (such as C-reactive protein (CRP)) that may also contribute to atherosclerosis." (PMID 24886106, 2014). "In addition, some studies have shown a correlation between subclinical atherosclerosis and selected proinflammatory factors such as C-reactive protein (CRP), fibrinogen, tumor necrosis factor-α (TNF-α), and interleukin-6 (IL-6)." (PMID 24772446, 2014). "Atherosclerosis possesses a fundamental chronic inflammatory aspect, and the involvement of numerous inflammatory molecules has been studied in this scenario, particularly C-reactive protein (CRP)." (PMID 27433484, 2014). "Nevertheless, this study using hypercholesterolemic rabbits still cannot answer the question of whether CRP is a mediator or a marker of atherosclerosis." (PMID 24872599, 2014). "CRP may intervene in atherosclerosis by directly activating the complement system and inducing apoptosis, vascular cell activation, monocyte recruitment, lipid accumulation, and thrombosis, among other actions." (PMID 27433484, 2014). "In ApoB100/100Ldlr−/− mice, CRP slowed the development of atherosclerosis." (PMID 24948846, 2014). "In addition to atherosclerosis, CRP along with complement activation has been shown to accelerate myocardial infarction in rats and targeting CRP can prevent CRP-induced myocardial injury." (PMID 24872599, 2014). "Hyperproduction of inflammatory markers such as C-reactive protein, interleukin-1 (IL-1), interleukin-6 (IL-6) and tumour necrosis factor-α (TNF-α) can be considered risk factors and some are directly related to the severity of atherosclerosis." (PMID 24642982, 2014). "Elevated CRP serum levels may promote atherosclerosis through its effect on adhesion molecule expression, since it has been shown that CRP induces ICAM-1 expression in coronary artery endothelial cells." (PMID 25490200, 2014). "The role of C-reactive protein (CRP) in atherosclerosis is controversially discussed." (PMID 24799767, 2014). "There is no consensus about the threshold level of CRP level for predicting the risk of atherosclerosis." (PMID 25299643, 2014). "Likewise, the genes enriched in bacterial cell surface binding pathway have relevance to the CRP level (CRP), atherosclerosis (CD36) and inflammation (PCSK6)." (PMID 24763700, 2014). "Many controversial and contradictory results using transgenic mice and rabbits have been published but it is also unclear whether CRP lowering can be used for the treatment of atherosclerosis." (PMID 24872601, 2014). "Administration of exogenously prepared CRP mutant may be useful to capture atherogenic LDL to prevent atherosclerosis." (PMID 24948846, 2014). "Several lines of evidence showed that CRP may modulate the vascular functions and thereby influence the initiation and progression of atherosclerosis." (PMID 24872601, 2014). "However, in a previous study, chronic unpredictable stress accelerated atherosclerosis by increasing serum levels of CRP in apolipoprotein E knockout mice." (PMID 25189624, 2014).